RNU1-124P (RNA, U1 small nuclear 124, pseudogene)
Gene: Small nuclear RNA gene on chromosome 8 (43,073,474 to 43,073,618, forward strand). Ensembl gene ENSG00000200731.
Homologues: Orthologues: chimpanzee U1 (94% identical), macaque U1 (83% identical). Paralogues in human: RNU1-148P (86% identical), RNU1-1 (85% identical), RNU1-2 (85% identical), RNU1-27P (85% identical), RNU1-28P (85% identical), RNU1-3 (85% identical), RNU1-4 (85% identical), RNVU1-18 (85% identical), RNVU1-29 (85% identical), RNVU1-7 (85% identical), U1 (85% identical), RNU1-89P (84% identical), and 134 more.